ZNF546 (zinc finger protein 546)
Description:
May be involved in transcriptional regulation.
Synonyms: ZNF49; MGC43537
Tractability: PROTAC: UniProt records ubiquitination sites on it; ubiquitination databases record sites on it.
Gene: Protein-coding gene on chromosome 19 (39,984,134 to 40,021,038, forward strand). Ensembl gene ENSG00000187187.
Subcellular location: Nucleus
Subcellular location (Human Protein Atlas): Nucleoplasm; Cytosol
Pathways (Reactome):
Gene expression (Transcription): Generic Transcription Pathway
Gene Ontology:
Molecular function: DNA-binding transcription factor activity, RNA polymerase II-specific; RNA polymerase II cis-regulatory region sequence-specific DNA binding
Biological process: regulation of transcription by RNA polymerase II; regulation of DNA-templated transcription
Cellular component: nucleus; nucleoplasm
Genetic constraint (gnomAD): Loss-of-function variants: 53 observed, 72.17 expected, observed/expected ratio (o/e) 0.73, 90% interval 0.59 to 0.92. The synonymous counts are far from expectation, so gnomAD's model fits this gene poorly and the ratio says little. Missense variants: 919 observed, 1,064.3 expected, observed/expected ratio (o/e) 0.86, 90% interval 0.82 to 0.91. Synonymous variants: 273 observed, 338.07 expected, observed/expected ratio (o/e) 0.81, 90% interval 0.73 to 0.89.
Homologues: Orthologues: chimpanzee ZNF546 (99% identical), macaque ZNF546 (93% identical), pig ZNF546 (83% identical). Paralogues in human: ZNF540 (42% identical), ZNF841 (42% identical), ZNF836 (42% identical), ZNF30 (41% identical), ZNF571 (40% identical), ZNF267 (38% identical), ZFP14 (37% identical), ZNF573 (37% identical), ZNF658 (37% identical), ZFP30 (37% identical), ZNF616 (36% identical), ZNF470 (36% identical), and 164 more.
Diseases named in the same sentence as ZNF546 in open-access papers:
ZNF546 is named in the same sentence as 3 diseases in open-access papers, as found by Europe PMC text mining. Sharing a sentence is not in itself a finding about the gene and the disease. The quoted sentences say what the papers report.
Autoimmunity (1 paper, 2018). The occurrence of an immune reaction against the organism's own cells or tissues. "ZNF546 encodes for a transcription factor of the ZNF family that has not been associated with autoimmunity or kidney disease." (PMID 29953444, 2018).
ZNF546 also shares sentences with these, for which no sentence is quoted: kidney disease (1 paper); tumor (1).